DMD (dystrophin)
Diseases named in the same sentence as DMD in open-access papers (continued):
Sharing a sentence is not in itself a finding about the gene and the disease.
cardiomyopathy (continued). "Although all DMD teenagers have signs of cardiac dysfunction, and up to 40% of patients may die from heart complications, cardiac involvement has not been studied as extensively as skeletal muscle disease, and the pathogenesis of dystrophin-deficient cardiomyopathy is not completely understood." (PMID 34947929, 2021). "Therefore, extra attention should be paid when one considers modelling cardiomyopathies that resulted from the gene mutation that may affect calcium transients, such as DMD." (PMID 34360897, 2021). "The association of cardiomyopathy with specific mutations in the DMD gene remain unclear." (PMID 32443516, 2020). "Finally, even if it becomes possible to achieve complete cardiac transduction and lasting expression of these DMD micro-genes, the treated patient population will still be at a similar risk for developing cardiomyopathy as BMD and XLCM patients due to the extensive truncation of the gene." (PMID 31443395, 2019). "Further study can also focus on identifying whether the HLA allele is involved in the pathogenesis of cardiomyopathy and neurodevelopmental disorders, which are secondary symptoms in DMD and show diverse clinical manifestations even when patients have the same DMD mutation." (PMID 30498470, 2018). "Also, dystrophin reduction has been observed in several experimental models of cardiomyopathies, such as post-viral myocarditis caused by Coxsackie virus B, myocardial infarction, isoproterenol and doxorubicin administration, septic cardiomyopathy and experimental Chagas disease." (PMID 29267303, 2017). "The precise relationship between mutations in the DMD gene and cardiomyopathy remain unclear." (PMID 26066469, 2015). "This case report highlights the complex interplay between genetic variants in the DMD and TNNI3K genes, resulting in extremely early onset of cardiomyopathy in a patient with DMD." (PMID 40134720, 2025). "When PWS coincides with DMD carrier status, additional surveillance for cardiomyopathy and muscular dystrophy is warranted." (PMID 41244984, 2025). "Studies have shown that as little as 4–15% dystrophin expression in cardiomyocytes can delay or ameliorate cardiomyopathy, while expression in ~50% of cardiomyocytes can prevent it." (PMID 40940738, 2025). "Some notable examples include combinations of DMD variants with titin (TTN) truncating variants, which typically present with early-onset muscle weakness and severe cardiomyopathy." (PMID 40134720, 2025). "These recapitulate the progression of DMD cardiomyopathy because this treatment is weakly effective in the heart, whereas it allows the correct rescue of dystrophin in the diaphragm and skeletal muscle." (PMID 40562489, 2025). "These mice replicate the progression of DMD cardiomyopathy, as the treatment has limited effectiveness in the heart, although it successfully rescues dystrophin in the diaphragm and skeletal muscle." (PMID 40562489, 2025). "Since emerging therapies are thus far unable to completely restore the DMD gene, there remains a need to develop additional therapies treating secondary contributors to cardiomyopathy." (PMID 39056750, 2024). "This DMD ΔEx51 rabbit model suffered from reduced dystrophin expression, histological defects, impaired physical activity, cardiomyopathy, and premature death." (PMID 38786024, 2024). "The DBA/2J-mdx (D2.mdx) and utrophin–dystrophin double-knockout mice have drawn attention as representing better models of DMD-induced cardiomyopathy, including earlier-onset cardiac deficits." (PMID 39056750, 2024). "Single-cut exon skipping was shown to be effective primarily at restoring dystrophin in the heart, completely preventing onset of cardiomyopathy in treated mice." (PMID 37545481, 2023). "Cardiomyopathy can occur in dystrophin- and sarcoglycan-related muscular dystrophy, and it is also associated with fibrotic and adipogenic deposition in the ECM." (PMID 37746696, 2023).
cardiomyopathy (continued). "Cardiomyopathy is characterized by qualitative defects and/or quantitative abnormalities of dystrophin in the myocardium." (PMID 36672955, 2023). "Restoration of dystrophin function is critical to prevent the progressive muscle weakness, respiratory insufficiency, and cardiomyopathy seen in patients with DMD." (PMID 37538053, 2023). "When the dystrophin complex is disrupted, cardiomyopathy, like skeletal muscle, is characterized by dysregulated intracellular calcium, which contributes to heart dysfunction." (PMID 37746696, 2023). "Proof of principle has been established in preclinical studies showing that shortened forms of dystrophin (micro-dystrophin) have the potential to ameliorate muscle pathology and cardiomyopathy when delivered in multiple DMD animal models." (PMID 37670674, 2023). "In this work, we have studied the Ca-Ts and APs recorded from DMD hiPSC-CMs obtained from a patient with DMD-related cardiomyopathy, carrying a deletion of exon 50 (Δ exon 50) in DMD gene." (PMID 36419836, 2022). "Rescue of skeletal muscles with a functional dystrophin transgene has been shown to exacerbate the onset of cardiomyopathy in mdx mice due to increased stress on the heart resulting from normal activity." (PMID 33651713, 2021). "DMD and LAMP2 mutations are very rare causes of DCM; notably, most known DCM-causing mutations affect the sarcomere, causing cardiomyopathy through impaired force generation or reduced contractility in the heart." (PMID 33467574, 2021). "In inherited neuromuscular disorders such as DMD and BMD the development of a cardiomyopathy and/or heart failure is the second most important cause of death after respiratory failure." (PMID 34743704, 2021). "It must be clarified that in this study, dystrophin was used exclusively as a marker to evaluate cardiomyopathy." (PMID 34063460, 2021). "Assessment of changes occurring in cardiac muscle in mdx mouse model suggested that restoration of cardiac myocyte dystrophin levels as low as 4–15% of the wild type mice can delay or even partially ameliorate the effects of cardiomyopathy in the mdx mice." (PMID 31612351, 2019). "Cardiomyopathy in early adulthood is a leading cause of death for DMD, responsible for 20–50% of mortalities in dystrophin-deficient patients." (PMID 30745312, 2019). "Particularly, rAAV9 seemed to be more effective in terms of heart transduction efficiency and was successfully used to treat cardiomyopathy in neonatal and adult mdx mice using micro-dystrophin." (PMID 30235804, 2018). "Different from Mdx mice, the DMD KO rabbits showed clear cardiomyopathy at 4 months of age, as evidenced by reduced left ventricular ejection fraction (EF) and fractional shortening (FS)." (PMID 29871865, 2018). "This work demonstrates that high levels of cardiac dystrophin restored by Pip peptide-AOs prevents further deterioration of cardiomyopathy and pathology following exercise in dystrophic DMD mice." (PMID 25758104, 2015). "Our data suggests that restoring high levels of dystrophin protein in heart is likely to prevent the progression of cardiomyopathy in DMD patients." (PMID 25758104, 2015). "Repeated peptide-AO treatments resulted in high levels of cardiac dystrophin protein, which prevented the exercised induced progression of cardiomyopathy, normalising heart size as well as stabilising other cardiac parameters." (PMID 25758104, 2015). "Using stringent statistical measures, our results demonstrate that restoring high levels of dystrophin in heart with Pip6-PMO was sufficient to prevent exercise-induced progression of cardiomyopathy and to improve multiple indices of cardiac pathology." (PMID 25758104, 2015). "More recently, the Pip6 series has demonstrated dystrophin expression in the heart at very low doses (12.5 mg/kg) and prevented exercise-induced cardiomyopathy following long-term treatment." (PMID 25988613, 2015).
cardiomyopathy (continued). "The three cardiomyopathies share a number of components associated with TOP2B2 peaks; these include dystrophin (DMD), integrins, and the sarcoglycan complex." (PMID 26459242, 2015). "Such a correlation between the structural features of mutated dystrophin and clinical severity in a cohort of BMD patients has been reported for cardiomyopathy." (PMID 22776072, 2012). "These chickens with cardiomyopathy had rupture of the dystrophin and other genes that regulate cell growth and differentiation." (PMID 21468314, 2011). "Hence, it is crucial to increase awareness of a possible cardiomyopathy in DMD carriers, even if asymptomatic." (PMID 40035839, 2025). "In DMD, the absence of dystrophin, a subsarcolemmal protein, induces progressive muscle degeneration, leading to the loss of independent walking, respiratory insufficiency, and cardiomyopathy during adolescence or early adulthood." (PMID 38687374, 2025). "In addition, around 10% of DMD female carriers exhibit certain clinical manifestations of the disease like mild weakness, isolated cardiomyopathy or cognitive involvement." (PMID 38687374, 2025). "Females with DMD gene variations, even in the absence of skeletal muscle symptoms, have an estimated 7.3–16.7% lifetime risk of developing cardiomyopathy, characterised by left ventricular dilatation and decreased shortening fraction." (PMID 40035839, 2025). "Vamorolone, developed for clinical use through preclinical trials in mdx mice, provides a drug that could safely treat chronic inflammatory signaling, muscle pathology, weakness, cardiomyopathy, and low dystrophin levels in BMD." (PMID 37534133, 2023). "A cleavage-resistant dystrophin knock-in mouse was revealed to have a decrease in sarcolemmal disruption and cardiac virus titer following Coxsackievirus infection linking the 2A proteolytic cleavage of dystrophin to the development of cardiomyopathy." (PMID 36851756, 2023). "The incidence of cardiomyopathy in DMD carriers increases with age." (PMID 37772130, 2023). "DMD manifests as childhood-onset muscle degeneration, followed by loss of ambulation, cardiomyopathy, and death in early adulthood due to a lack of functional dystrophin protein." (PMID 35163754, 2022). "As an example of severe cardiomyopathy with early onset, we compared hiPSC-CMs generated from a DMD patient (DMD-ΔExon50) and a CRISPR-Cas9 genome edited cell line isogenic to the healthy control with deletion of a G base at position 263 of the DMD gene (c.263delG-CMs)." (PMID 36419836, 2022). "The fact that contractile deficiency was only apparent in DMD hiPSC-CMs cultured on 35 kPa substrates suggests that DMD cardiomyocytes are unable to compensate for dystrophin deficiency once the heart tissues undergo fibrotic stiffening, a hallmark of DMD cardiomyopathy." (PMID 34019816, 2021). "While Linc-RAM has not been directly associated with cardiomyocytes, MyoD-null dystrophin-null transgenic mice develop severe cardiomyopathy." (PMID 34364390, 2021). "However, in both dystrophin-deficient and dystrophin/utrophin-deficient hearts, the DGC remains localized to cardiomyocyte membranes, despite that mutations of some DGC members also lead to cardiomyopathy." (PMID 33651713, 2021). "Congruent with our previous reports, we have confirmed that the lack of dystrophin in mdx cardiomyocytes with proven cardiomyopathy causes an age-dependent [Ca2+]d and [Na+]d overload (15-month > 12-month > 3-month) compared with age-matched WT cardiomyocytes." (PMID 34017265, 2021). "Dystrophin-deficient mdx mice exhibit only a mild cardiomyopathy that never advances into reduced whole heart function." (PMID 33651713, 2021). "On the other hand, we are also conscious that subjects with DMD gene mutation-related cardiomyopathy have normal or near normal CK, so that they cannot be identified by this programme." (PMID 32112218, 2020). "It was indicated that cardiomyopathy is dystrophin isoform specific." (PMID 32443516, 2020).
cardiomyopathy (continued). "The incidence of cardiomyopathy induced by DMD increases with age." (PMID 32650783, 2020). "Thus, manifestation of skeletal muscle wasting, but also cardiomyopathy occurs in males, while female carriers of the defective DMD gene are perceived healthy." (PMID 33247228, 2020). "It was shown that, in mdx mice, as little as 20% of the wild-type dystrophin level was effective in the prevention of disease progression when the creatine kinase level and fiber degeneration were assessed, but for cardiomyopathy treatment, this level should exceed 50%." (PMID 32691346, 2020). "These dystrophin-deficient models have a natural late onset of cardiomyopathy, and therefore are not suitable tools to study cardiac implications of these strategies." (PMID 32988972, 2020). "Given the relevance of cross-linkers in determining the physical properties of a cell, we hereby review the cases of inherited cardiomyopathies caused—or likely caused—by aberrant actin-binding and crosslinking proteins, namely alpha-actinin 2 (ACTN2), filamin C (FLNC) and dystrophin." (PMID 32824180, 2020). "These limitations on the maximal theoretical efficacy of AAV gene therapy for DMD may result in the continued need for additional small molecule-based management of cardiomyopathy in the setting of an otherwise mild BMD-like phenotype." (PMID 31443395, 2019). "Female carriers of dystrophin mutations do not present with severe paralysis like affected males, but often present with symptoms of cardiomyopathy as a result of uneven expression of wild-type and mutant versions of dystrophin throughout the muscle." (PMID 31546754, 2019). "Notably, female BMD and DMD carriers, who are mostly free of skeletal muscle symptoms, are also prone to cardiomyopathy development." (PMID 30360568, 2018). "In addition, these mice frequently are easier to work on, as the cardiomyopathy symptoms occur earlier in life in comparison to dystrophin only models, making the work less expensive and less time consuming." (PMID 29367539, 2017). "Cardiomyopathy that occurs without skeletal muscle involvement is frequently caused by missense mutations in the dystrophin gene." (PMID 22691118, 2012). "Patterns of enhancement included epicardial, similar to the pattern seen in dystrophin-deficient cardiomyopathy and some myocarditis, as well as the midwall fibrosis of other nonischemic cardiomyopathies." (PMID 21816046, 2011). "Consequently, mdx mice lack full-length dystrophin and develop a late onset and progressive cardiomyopathy that has some similarity with that observed in human dystrophic patients." (PMID 22066028, 2011). "It remains unclear whether dystrophin genotype can predict the course of cardiomyopathy." (PMID 40729215, 2024). "However, no prospective trials have been completed, and steroids are not currently indicated in the setting of isolated dystrophin-deficient cardiomyopathy." (PMID 35549971, 2022). "Hereby, we have reported what has already been discovered about ACTN2, FLNC and dystrophin in inherited cardiomyopathies and our effort might set the stage for broadening the panel of screened genes in cardiomyopathy patients by including the genes that code for other cytoskeletal cross-linkers." (PMID 32824180, 2020). "Despite dystrophin being the primary target gene in many (but not all) of these models and cardiomyopathy being the most common cause of death, very few have DCM as the only symptom, despite so many animals naturally occurring with DCM only in normal populations." (PMID 29367539, 2017). "Sporadic manifestation of cardiomyopathy, including dilated cardiomyopathy (DCM), is one of the major features of DMD carriers, and its occurrence increases with age." (PMID 37772130, 2023).
cardiomyopathy (continued). "However, the healthy status of this carrier on the dystrophin protein should not be overstated, considering that mutations at 5′ of the gene may result in cardiomyopathies, and in this case there may be a compensative effect of the hypomorphic maternal allele." (PMID 33494189, 2021). "In fact, a significant correlation was found between cardiomyopathy and skewed XCI assessed in leukocytes in BMD/DMD carriers, suggesting that the analysis of XCI in this tissue can be useful to predict the phenotype." (PMID 34299283, 2021). "Due to the prevalence of cardiomyopathy among patients with DMD, successful dystrophin restoration in the heart is an important aspect of the potential clinical benefits of gene therapies." (PMID 33898631, 2021). "Adeno-associated virus (AAV)-mediated systemic administration of microdystrophin, which functionally substitutes for dysfunctional dystrophin in DMD, demonstrates amelioration of muscle pathology, enhancement of contractile force, and attenuation of cardiomyopathy in preclinical models." (PMID 40868246, 2025). "This analysis allowed distinguishing the differences driving the onset of mild and severe cardiac muscle degeneration and cardiomyopathy, independent of the presence/absence of dystrophin protein." (PMID 40634289, 2025). "On the other hand, DMD cardiomyopathy should be characterized by an absence of dystrophin, which is distinct from other forms of dilated cardiomyopathies (DCM)." (PMID 40863346, 2025). "Necrosis and fibrosis of dystrophin-negative cardiomyocytes are likely to be involved in cardiomyopathy in DMD carriers, similar to male DMD patients." (PMID 37772130, 2023). "Accordingly, this potentially elucidates a mechano-transduction mechanism by which myocytes lacking dystrophin have a greater propensity for ventricular damage and consequent cardiomyopathy leading to failure." (PMID 37362434, 2023). "We have previously demonstrated that WBPA-elicited NO production alleviated the cardiomyopathy’s severity in mice lacking both dystrophin and utrophin protein expression." (PMID 34017265, 2021). "The prevalence of cardiomyopathy in female DMD carriers varies in wide range and does not correlate with phenotype, muscle symptoms, creatinine kinase levels or age13,15,29." (PMID 33247228, 2020). "DMD carrier fetuses had obstetric outcomes similar to DMD negative female fetuses; however, close follow-up for the management of complications, like muscle weakness and cardiomyopathy, should be planned for these patients." (PMID 30151283, 2018). "Current therapies for cardiomyopathy in DMD are non-specific, but P188 directly targets membrane instability which is known to be one of the major pathological defects in dystrophin deficient cells." (PMID 21575230, 2011). "Hearts from aging mdx heterozygous mice, which express dystrophin in 50% of the cardiomyocytes, unlike those from mdx mice, do not develop cardiomyopathy." (PMID 19277212, 2009). "These hiPSC-derived cardiomyocytes (hiPSC-CMs) exhibit a functional dystrophin–glycoprotein complex (DGC) localized to the membrane, show electrophysiological abnormalities and arrhythmogenicity, and reproduce phenotypes observed in patients with DMD cardiomyopathy." (PMID 40940738, 2025). "Currently, there is no approved DMD-specific treatment for cardiomyopathy, although several new types of ASOs, such as peptide-conjugated ASOs, may provide potential benefits." (PMID 40940738, 2025). "Similarly, the absence of dystrophin leads to structural and functional alterations of cardiomyocytes, resulting in a severe cardiomyopathy." (PMID 36902405, 2023). "Furthermore, the cardiomyopathy phenotype development depends not only on the absence of dystrophin but also on the detrimental effects of non-cardiomyocyte subpopulations." (PMID 36035984, 2022).